MROH8 (maestro heat like repeat family member 8)
Synonyms: C20orf131; C20orf132; dJ621N11.4; dJ621N11.3
Gene: Protein-coding gene on chromosome 20 (37,101,226 to 37,179,588, reverse strand). Ensembl gene ENSG00000101353.
Subcellular location (Human Protein Atlas): Nucleoplasm; Cytosol; Vesicles
Genetic constraint (gnomAD): Loss-of-function variants: 45 observed, 67.81 expected, observed/expected ratio (o/e) 0.66, 90% interval 0.52 to 0.85. The upper end of that interval is the gene's LOEUF score, 0.85, which puts it in group 3 of 6, group 1 being the genes least tolerant of losing a copy. Missense variants: 613 observed, 740.84 expected, observed/expected ratio (o/e) 0.83, 90% interval 0.77 to 0.88. Synonymous variants: 255 observed, 286.72 expected, observed/expected ratio (o/e) 0.89, 90% interval 0.8 to 0.99.
Homologues: Orthologues: macaque MROH8 (94% identical), chimpanzee MROH8 (83% identical), dog MROH8 (75% identical), guinea pig MROH8 (73% identical), rat Mroh8 (70% identical), mouse Mroh8 (69% identical), rabbit MROH8 (65% identical). Paralogues in human: MROH7 (23% identical), MROH1 (22% identical), MROH5 (20% identical), MROH2B (19% identical), MROH2A (18% identical), MROH9 (16% identical), MROH6 (14% identical), MRO (4% identical).
Diseases named in the same sentence as MROH8 in open-access papers:
MROH8 is named in the same sentence as 8 diseases in open-access papers, as found by Europe PMC text mining. Sharing a sentence is not in itself a finding about the gene and the disease. The quoted sentences say what the papers report.
Alzheimer disease (1 paper, 2021). A progressive, neurodegenerative disease characterized by loss of function and death of nerve cells in several areas of the brain leading to loss of cognitive function such as memory and language. "Genomewide association studies (GWASs) previously linked MROH8 (Maestro heat‐like repeat‐containing protein family member 8) to Alzheimer's disease, whereas the exact function of NUTM2G is not known." (PMID 33778321, 2021).
glioblastoma (1 paper, 2024). The most malignant astrocytic tumor (WHO grade IV). "MROH8 was identified as part of a gene expression signature related to temozolomide sensitivity in glioblastomas, providing potential prognostic value and therapeutic guidance for patient survival." (PMID 39434688, 2024).
lung carcinoma (1 paper, 2020). "In contrast, blood cell traits and hematological diseases were implicated with a wider range of loci, including TERC, TERT, SENP7, ATM, BBOF1, and MROH8; this result is similar to those for the respiratory function and lung cancers that also involved multiple TL loci." (PMID 32109421, 2020).
pancreatic cancer (1 paper, 2024). "Additionally, MROH8 was associated with improved survival in pancreatic cancer patients, supporting our hypothesis." (PMID 39434688, 2024). "Subsequent experiments confirmed this hypothesis; we found that METTL16 inhibits CAPN2 expression by regulating MROH8, which in turn affects the progression and metastasis of pancreatic cancer." (PMID 39434688, 2024). "Additionally, our METTL16 RIP-qPCR data demonstrated strong binding between METTL16 protein and MROH8 transcripts in pancreatic cancer cells." (PMID 39434688, 2024). "In conclusion, this study uncovers a novel regulatory pathway in pancreatic cancer involving METTL16, MROH8, TBP, and m6A modifications." (PMID 39434688, 2024). "This study thus proposes a novel regulatory axis involving METTL16, MROH8, and CAPN2, expanding our understanding of how m6A modifications influence pancreatic cancer progression and offering potential new therapeutic targets." (PMID 39434688, 2024). "This study reveals a novel regulatory axis involving METTL16, MROH8, and TBP that modulates CAPN2 expression, contributing to the suppression of pancreatic cancer progression." (PMID 39434688, 2024).
cancer (2 papers, 2011 to 2024). A tumor composed of atypical neoplastic, often pleomorphic cells that invade other tissues. "Specifically, we aim to investigate how METTL16, an m6A writer gene, interacts with key downstream targets, such as CAPN2 and MROH8, to influence cancer metastasis." (PMID 39434688, 2024). "The discovery of MROH8’s involvement in TBP regulation adds a new dimension to the understanding of TBP function in cancer." (PMID 39434688, 2024).
tumor (1 paper, 2024). "This study aims to elucidate the role of METTL16, an m6A writer gene, in regulating core genes such as CAPN2 and MROH8, influencing tumor growth and metastasis." (PMID 39434688, 2024). "Functional assays demonstrated that METTL16 and YTHDC2 (an m6A reader) collaboratively enhanced MROH8 mRNA stability, thereby inhibiting CAPN2 expression and reducing tumor proliferation and metastasis (P<0.001)." (PMID 39434688, 2024). "METTL16 overexpression significantly inhibited tumor growth and metastasis (P<0.001) by downregulating CAPN2 through an indirect mechanism involving the transcription factor TBP and the gene MROH8." (PMID 39434688, 2024).
MROH8 also shares sentences with these, for which no sentence is quoted: hematological diseases (1 paper); hippocampal atrophy (1).